ACHE (acetylcholinesterase (Yt blood group))
Diseases named in the same sentence as ACHE in open-access papers (continued):
Sharing a sentence is not in itself a finding about the gene and the disease.
memory impairment (continued). "This study focuses on investigating the potential of astragaloside IV (AIV), a triterpenoid saponin with proven acetylcholinesterase (AChE)-inhibiting activity naturally occurring in the root of Astragalus mongholicus, to attenuate memory impairment." (PMID 38612831, 2024). "Several studies have mentioned ACh/AChE imbalance to alter hippocampal function, resulting in memory impairment related to various neurodegenerative disorders such as Alzheimer’s." (PMID 38114728, 2024). "Collectively, these findings suggest that treatment with MT‐01 can ameliorate the impact of chemically induced memory impairment of KM mice, evidenced not only by a cognitive performance assay, but also by reduced AChE activity and increased SOD activity." (PMID 39055226, 2024). "Accumulation of amyloid beta (Aβ) in neurons is the major cause of Alzheimer’s disease (AD), and increased acetylcholinesterase (AchE) activities in AD lead to memory impairment." (PMID 39195183, 2024). "It has been observed that Ach levels drastically decreased in AD patients due to increased AchE enzyme activity, leading to cognition and memory impairment." (PMID 39195183, 2024). "All changes, including oxidative stress, inflammation, apoptosis, Erk signaling, and AChE, play roles in neurodegeneration and memory impairment." (PMID 39683536, 2024). "The results revealed that MEDF and AFDF exhibit anxiolytic effects and significantly alleviated Sco-induced memory impairment, inhibited AChE in the cortex (40%) and MDA (51.51%) levels." (PMID 39765648, 2024). "The extracts significantly ameliorated scopolamine-induced memory impairments, protecting against antioxidant enzymes and inhibiting the AChE enzyme." (PMID 39771015, 2024). "Our results also show that OVX/D-Gal group rats demonstrated an upsurge of hippocampal AChE content with subsequent cognitive and memory impairments." (PMID 38294617, 2024). "In a relative study, EDV treatment in ICV-STZ rats managed to attenuate MDA levels and recover GSH levels in brain hippocampus, while also retrieving NO levels and AChE activity leading to restoration of blood flow as well as memory impairment." (PMID 37476485, 2023). "Medications that are commonly used clinically to prevent and improve learning in learning and memory impairments include free radical scavengers, acetylcholinesterase (AChE) inhibitors and drugs to prevent the formation of amyloid β deposits." (PMID 37569204, 2023). "In vitro, myrtenal has been shown to exert an inhibitory effect on AChE activity, suggesting its beneficial effect on memory impairment." (PMID 35204256, 2022). "Sesamin is a phytochemical found in Cortex Acanthopanacis radicis, is reported to inhibit AChE, and known to improve memory impairment in mouse." (PMID 35617284, 2022). "In conclusion, it reveals that the TN extract can significantly attenuate Scop-induced memory impairments by diminishing Aβ aggregates, as well as its anti-inflammatory, antioxidant, anti-apoptotic and anti-AChE activities." (PMID 36296710, 2022). "The clinically used anti-dementic drug donepezil ameliorated the scopolamine-induced memory impairment by reducing AChE activity and oxidative stress and restoring the cerebral circulation." (PMID 36005148, 2022). "In conclusion, the present study reveals that TN extract attenuates Scop-induced memory impairments by diminishing amyloid beta aggregates, as well as its anti-inflammatory, antioxidant, anti-apoptotic and anti-AChE activities." (PMID 36296710, 2022). "In in vivo studies, it has exhibited strong antioxidant and anticholinesterase potential and was capable of reversing scopolamine-induced learning and memory impairments through reduction of brain cholinesterases (AChE and BChE) enzymes level." (PMID 33669503, 2021). "We evaluated the effects of AH leaf and root extracts on ACh concentration and AChE activity in serum of mice with memory impairment induced by scopolamine." (PMID 34445062, 2021).
memory impairment (continued). "Phlorotannin-rich extract from Ishige foliacea improved the cognitive function by upregulating the ERK/CREB/BDNF signaling pathway and preventing the AChE activity and oxidative stress on the scopolamine-induced learning and memory impairment mouse model." (PMID 33673531, 2021). "Another form of lithium, lithium carbonate (Li2CO3), has been demonstrated to prevent memory impairment and AChE activity in zebrafish induced by scopolamine." (PMID 34335276, 2021). "Our data indicated that both COT and 6HLN attenuated the SCOP-induced anxiety-like behavior and memory impairment and reduced the oxidative stress and AChE activity in the brain of zebrafish." (PMID 33535660, 2021). "Huperzine A, a natural acetylcholinesterase (AChE) inhibitor, suppresses the overexpression of TNFα and protects against 2VO-induced memory impairment." (PMID 34030135, 2021). "The increased level of AChE activity in such rats suggested that quercetin can prevent memory impairment and change lipid metabolism." (PMID 34206761, 2021). "A previous study stated that SCO-induced memory impairment was reversed via the inhibition of AChE by donepezil-treatment." (PMID 34290261, 2021). "Unfortunately, current therapeutic approaches for AD remain still limited to the symptomatic treatment of memory impairment by acetylcholinesterase (AChE) inhibitors, namely donepezil, rivastigmine and galantamine, and of glutamate excitotoxicity by memantine." (PMID 33297547, 2020). "Our results are the first to show that AChE activity in the SP-induced memory impaired model are effectively suppressed by administration of GEGR for three weeks." (PMID 31623364, 2019). "Another study reported that pretreatment with anthocyanins prevents scopolamine-induced memory impairment, decreases AChE activity in the cortex and hippocampus, and restores hippocampal Na+, K+-ATPase, and Ca2+-ATPase activities." (PMID 34466529, 2019). "Then it is postulated that scopolamine-induced oxidative stress is a possible mechanism of AChE activity increase and subsequent memory impairment." (PMID 29942435, 2018). "Increased level of AChE metabolizes more acetylcholine and reduces its level in the synapses then weakens cholinergic neurotransmission which resulted in memory impairment." (PMID 29942435, 2018). "It has been already reported that inhibition of AChE activity by plants and their constituents are effectively able to repair the memory impairment induced by scopolamine." (PMID 29875670, 2018). "In summary, scopolamine produced severe deficits in the performance of mice in the Morris water maze test, along with signs of memory impairments, including changed AChE activity and altered PI3K and ERK/CREB/BDNF pathways in the hippocampus." (PMID 29670659, 2018). "Depletion of acetylcholine (ACh) together with the elevation of acetylcholinesterase (AChE) in the PFC induces memory impairment both in primates and in rodents." (PMID 28770022, 2017). "The results showed that CSGNL significantly ameliorated scopolamine-induced learning and memory impairment, at least in part, by modulating ACh levels and ChAT and AChE activities in the mouse brain." (PMID 28814961, 2017). "It was found that MME decreased memory impairment, oxidative stress status, and AChE activity but increased neuron density and Erk phosphorylation in the hippocampus." (PMID 29158872, 2017). "FCL significantly attenuated scopolamine-induced memory impairment in mice and prevented scopolamine-induced AChE activity in the hippocampus." (PMID 28716085, 2017). "The effect of A. melanocarpa berries extract on AChE activity in the hippocampus of scopolamine-induced memory-impaired mice was evaluated." (PMID 27239211, 2016). "Steamed and fermented C. lanceolata ameliorated amyloid-β–induced memory impairment and this effect appears to be mediated via the inhibition of AChE activity and the activation of BDNF, p-CREB, and ERK signaling." (PMID 27313637, 2016).
memory impairment (continued). "Aluminium induces memory impairment by decreasing cholinergic function, as measured by acetylcholinesterase (AChE) and choline acetyltransferase activities, the key enzymes involved in the degradation and synthesis of acetylcholine." (PMID 27893738, 2016). "Selenofuranoside was able to restore AChE activity as well as memory impairment observed in the Aβ group." (PMID 26090073, 2015). "We found that ENS significantly ameliorated scopolamine-induced memory impairment and inhibited AChE activity in hippocampus." (PMID 25610484, 2014). "Our data showed that TL prevented Pb induced memory impairment and AChE dysfunction in a dose-dependent manner, indicated by the in vitro and in vivo studies." (PMID 24455676, 2013). "In the present study, acupuncture stimulation to the HT7 acupoint significantly improved learning and memory retention in the MWM and increased ChAT and AchE immunoreactivities in the hippocampus areas of chronic CORT-induced memory impairment male rats." (PMID 22216057, 2012). "For example, a study published in Fish Physiology and Biochemistry showed that betanin treatment protected zebrafish against SCO (100 μM)-induced memory impairments and oxidative stress by normalizing AChE activity, enhancing BDNF expression, and reducing MDA levels." (PMID 41155598, 2025). "However, the increase in brain AChE activity has been shown to induce memory impairments and promote oxidative stress." (PMID 39820545, 2025). "Furthermore, in animal models, scop has been extensively utilized to induce learning and memory impairments by elevating the levels of Acetylcholinesterase (AChE) and lipid peroxidation (LPO) within the hippocampus." (PMID 41550299, 2025). "Finally, Nine-Herb Decoction, containing various plant extracts, and Prunella vulgaris aqueous extract have also exhibited protective effects against SCO-induced memory impairments by inhibiting AChE activity." (PMID 40002547, 2025). "Moreover, chlorogenic acid extract demonstrated neuroprotective effects by reducing AChE activity, oxidative stress, and memory impairment, while wild ginseng also improved learning and reduced cholinergic loss and AChE activity in the hippocampus." (PMID 40002547, 2025). "Aβ can also increase AChE activity in the hippocampus, prefrontal cortex, and amygdala, which may lead to memory impairment." (PMID 39199197, 2024). "C. longa extract, in doses of 100 or 200 mg/kg, has shown neuroprotective effects on scopolamine-induced memory impairment mice, evidenced by improved behaviors in the passive avoidance and Moris water maze tests by reducing AChE activity and inducing BDNF-CREB expression." (PMID 39457003, 2024). "It induces learning and memory impairments in animals and humans by elevating AChE activity, increasing oxidative stress, decreasing biogenic amine levels, and suppressing the expression of genes related to memory processes, such as BDNF and CREB, in the hippocampus and cortex." (PMID 38339117, 2024). "Indeed, Aβ oligomer-induced neuronal damage in mice treated with ginseng extract at doses of 100 and 500 mg/kg showed restoration of reduced synaptophysin and AChE intensity in the hippocampus, indicating that ginseng extract reverses memory impairment in AD." (PMID 39457003, 2024). "Recently, a 12-week ginseng supplementation demonstrated improved memory in subjects aged 55 to 75 years with subjective memory impairment, with significant differences in cognitive improvement and AChE levels observed in a randomized, double-blind, placebo-controlled clinical trial." (PMID 39457003, 2024). "It was shown that MO inhibited the oxidative stress state and the activity of AChE and BChE in the brain of model mice and improved the memory impairment induced by Sco by restoring the activity of the cholinergic system and the antioxidant status of the brain." (PMID 37009463, 2023).
memory impairment (continued). "Notably, a previous preclinical experiment in rodents showed that canagliflozin (10 mg/kg) noticeably downregulated hippocampal AChE activity in scopolamine-induced memory impairment model in rats." (PMID 37242552, 2023). "Currently, several acetyl-cholinesterase (AChE) inhibitors (donepezil, rivastigmine, and galantamine) and an N-Methyl-D-aspartate (NMDA) receptor antagonists (memantine) are used in aging-associated memory impairment." (PMID 35767571, 2022). "For this reason, the reduction of AChE may be involved in memory impairment since an excess level of ACh was shown to be neurotoxic." (PMID 35434276, 2022). "Here, we disclose a classof 6-chlorotacrine (huprine)–TPPU hybrids as dual inhibitorsof the enzymes soluble epoxide hydrolase (sEH) and acetylcholinesterase(AChE), a multitarget profile to provide cumulative effects againstneuroinflammation and memory impairment." (PMID 35271276, 2022). "In this study, we investigated whether the HE could inhibit the memory impairment induced by SCOP by inhibiting AChE or decreasing oxidative stress." (PMID 34204787, 2021). "There are also reports of AChE inhibitory activity of AH extracts, reducing oxidative stress, and having antioxidant and anti-inflammatory effects, but improving cognitive function in mice treated with memory impairment substances." (PMID 34445062, 2021). "- Recovering memory impairment induced by scopolamine, and its effect may be related to the ability of AChE inhibition." (PMID 30405389, 2018). "Studies indicate that AChE inhibitors can reverse scopolamine-induced memory impairment." (PMID 29942435, 2018). "Therefore, AChE inhibitors are potentially useful agents in the treatment of learning and memory impairments." (PMID 29670659, 2018). "Treatment with NKDB herbs which ameliorates memory impairment could increase the number of ChAT-positive cells, whereas decrease AChE activity and number of AChE-positive cells." (PMID 30298092, 2018). "High AChE activity plays an important role in memory impairment." (PMID 27313637, 2016). "Indeed, AChE inhibitors, including donepezil, galantamine, tacrine, and rivastigmine, can attenuate memory impairment by inhibiting the destruction of ACh." (PMID 27239211, 2016). "In addition, these memory impairments were recovered by cholinergic activation through treatment with AChE inhibitors." (PMID 26246157, 2015). "Scopolamine induced memory impairment by increased AChE activity." (PMID 25045391, 2014). "Therefore, we did suggest that laser acupuncture at HT7 improved memory impairment in animal model of PD via the suppression of AChE and MAO-B which in turn increased the function of cholinergic and dopaminergic systems." (PMID 25161693, 2014). "Further, in several of these models, the boswellic compounds were shown to rescue memory impairment through the inhibition of AChE, observations that are in line with in vitro research showing boswellic triterpenoids selectively dock to AChE and exhibit considerable AChE inhibition." (PMID 41438191, 2025). "Likewise, TSG, the major stibene compound of P. multiflorum, was reported to increase the levels of ACh and to inhibit the activity of AChE in a scopolamine-induced memory impairment mouse model, resulting in improved cholinergic function and memory performance." (PMID 41516109, 2025). "Also, kaempferol was speculated to act on the esterification subunit of AChE or ionic site and inhibits AChE activity for this reason, although its mechanism for improving of memory impairment was unclear." (PMID 38963536, 2024). "The Kleeb Bua Daeng formula (KBD), a Thai traditional medicine with multi-target activities could inhibit activities of the AChE, Aβ aggregation, the expression of pro-apoptotic factors in an in vitro study and show protective effects on memory impairment in animals." (PMID 39081953, 2024).
memory impairment (continued). "CMP scavenges oxygen free radicals, decreasing AChE activity in the mouse brain, which may reduce the damage of cholinergic neurological nerves, hence improving learning and memory ability in a scopolamine-induced mice model of learning and memory impairment." (PMID 37569204, 2023). "Spontaneous alternation performance among Crinum macowanii treated groups showed an increasing dose-dependent effect, suggesting that memory-enhancing activity of Crinum macowanii on memory impairments induced by scopolamine may be connected to the inhibition of AChE activity." (PMID 26558135, 2015). "We determined AChE inhibitory effects of ME that could potentially improve memory impairment in AD." (PMID 24386444, 2013). "For instance, in mouse models of scopolamine-induced memory impairment, the administration of SFN (10 or 50 mg/kg) to C57BL/6 mice via oral gavage for 2 weeks significantly reduced AChE activity in the frontal cortex." (PMID 38791068, 2024). "Lactobacillus fermentum LAB9 or Lactobacillus fermentum LABPC attenuated LPS-induced memory impairment in mice, increased the level of antioxidants and decreased the levels of MDA, AChE and proinflammatory cytokines." (PMID 37728579, 2024). "This study demonstrated that bilateral administration of STZ (icv) resulted in memory impairment, as indicated by changes in behavior in the ORT and inhibitory avoidance, as well as increased oxidative stress and activation of AChE and GFAP." (PMID 38391705, 2024). "Ni, Al and Ni/Al mixture exhibited memory impairment by activation of oxidative stress, COX-2, and diminution of AChE, BDNF and NGF levels in cerebral cortex and hippocampus." (PMID 37841055, 2023). "MetS rats with GCJ treatment improved memory impairment, enhanced neuron density, and increased the expressions of eNOS, BDNF, and pERK/ERK but suppressed AChE in both areas." (PMID 37564141, 2023). "In mice exposed to scopolamine-induced memory impairment, SFN increased acetylcholine (ACh) level, decreased acetylcholinesterase (AChE) activity, and increased choline acetyltransferase (ChAT) expression in the hippocampus and frontal cortex." (PMID 35163897, 2022). "In the same zebrafish model with memory impairment, Thymus vulgaris L. essential oil (TEO) ameliorated zebrafish amnesia and anxiety, reduced AChE activity and brain antioxidant capacity." (PMID 34335276, 2021). "Moreover, based on the phytochemical, behavioural, and biochemical results, we hypothesize that F. ammoniacum could possibly act directly as a free radical scavenger or regulator to inhibit cholinesterases (AChE and BChE), oxidative stress, and memory impairments induced by scopolamine." (PMID 33669503, 2021). "Another study investigated the ethanolic extract of its fruits on memory impairment in an AD mice model and found that the ethanolic extracts could improve the anti-amnesic activity in mice via the inhibition of lipid peroxidation and the decreased AChE activity in the brain." (PMID 34070275, 2021). "Taken together, the results of this study demonstrated that SS can prevent and protect against scopolamine-induced memory impairment by regulating the NGF-BDNF-CREB signaling pathway and inhibiting AChE expression." (PMID 30018265, 2018). "Administration of a low dose of MT‐01 was able to significantly improve the performance of sodium nitrite‐induced memory impairment in mice, as scored in behavioral tests, and also increase SOD activity and decrease AChE activity, compared to mice with sodium nitrite treatment." (PMID 39055226, 2024). "Importantly, MT‐01 was shown to ameliorate scopolamine‐induced memory impairment in behavioral tests, increase SOD activity, and decrease AChE activity in mice, compared to scopolamine‐treated mice with no MT‐01 administration." (PMID 39055226, 2024).